GPR39 (G protein-coupled receptor 39)
Diseases named in the same sentence as GPR39 in open-access papers (continued):
Sharing a sentence is not in itself a finding about the gene and the disease.
atherosclerosis (3 papers, 2021 to 2023). A disease characterized by the build-up of fatty material and calcium deposition in the arterial wall resulting in partial or complete occlusion of the arterial lumen. "In particular, GPR39 regulates vascular endothelial cell activity and vascular calcification, and it has anti‐atherosclerosis effect." (PMID 36942516, 2023). "Data in this study reveal the roles of GPR39 and A20 in atherosclerosis and provides evidence that GPR39 agonist is of great potential in the treatment of atherosclerosis." (PMID 34288802, 2021). "In a murine model of atherosclerosis, GPR39 mRNA expression was found to be increased in dedifferentiating VSMCs." (PMID 34360964, 2021). "The increase in GPR39 expression not only reduces the number of apoptotic macrophages but also inhibits the lipid accumulation of macrophages induced by ox‐LDL to slow down the progression of atherosclerosis." (PMID 36942516, 2023). "Outside of the central nervous system, GPR39 has been investigated in the vascular system for its regulation of inflammatory and proliferative tone in the setting of hypertension, turbulent blood flow, and atherosclerosis." (PMID 34360964, 2021). "Therefore, we speculated that GPR39 may participate in the regulation of atherosclerosis via an A20-dependent manner." (PMID 34288802, 2021). "A recent study pointed out that agonizing the G protein-coupled receptor 39 (GPR39) weakens oxidized low-density lipoprotein (ox-LDL)-induced attachment of monocytes to vascular endothelial cells and thus alleviates atherosclerosis." (PMID 34288802, 2021). "It has been reported that GPR39 weakens ox-LDL-induced attachment of monocytes to vascular endothelial cells and thus alleviates atherosclerosis." (PMID 34288802, 2021). "G protein-coupled receptor 39 (GPR39) agonist weakens oxidized low-density lipoprotein (ox-LDL)-induced attachment of monocytes to vascular endothelial cells and thus alleviates atherosclerosis." (PMID 34288802, 2021). "This study looks at whether GPR39 protects macrophages against ox-LDL-induced inflammation and apoptosis and ameliorates lipid accumulation in atherosclerosis and investigates its mechanism." (PMID 34288802, 2021). "In addition, according to a recent study, strengthening the expression of GPR39 with its agonist TC-G 1008 decreases the attachment of ox-LDL-challenged monocytes to endothelial cells, thus alleviating decelerating the development of atherosclerosis." (PMID 34288802, 2021). "However, the lack of data about the expression of GPR39 and A20 in the macrophage of patients with atherosclerosis (especially in high ox-LDL patients) is a limitation of the present study, which will be investigated in the next experiments to further support the conclusions in this study." (PMID 34288802, 2021).
colon cancer (3 papers, 2012 to 2022). "Finally, our results indicate that ZnR/GPR39 activation enhances survival of colon cancer cells by rendering them less susceptible to cell death induced by butyrate." (PMID 22545109, 2012). "In colon cancer cell lines, the activation of the ZnR/GPR39-dependent MAPK and PI3K pathways increases the expression of anti-apoptotic proteins (such as clusterin), thus, attenuating butyric acid-induced apoptosis." (PMID 36292986, 2022). "Similarly, ZnR/GPR39 activation of MAPK, PI3K and clusterin were shown to enhance survival of colon cancer cells following treatment with apoptosis-inducing butyrate." (PMID 29802348, 2018).
dementia (3 papers, 2021 to 2023). Loss of intellectual abilities interfering with an individual's social and occupational functions. "We have also implicated GPR39 in aging-related vascular cognitive impairment and dementia (VCID;)." (PMID 34360964, 2021). "As microglial GPR39 expression and signaling transduction pathways become better understood, the receptor becomes targetable as a potential mechanism to decrease dementia-related neuroinflammation." (PMID 34360964, 2021). "This can also be a direction for GPR39 to intervene in the diagnosis and treatment of dementia." (PMID 36942516, 2023).
gastric adenocarcinoma (3 papers, 2016 to 2022). "More recently, the obestatin/GPR39 system has been implicated in the pathogenesis of gastric adenocarcinomas, suggesting that obestatin regulates human gastric adenocarcinoma cells via GPR39." (PMID 35454106, 2022). "Furthermore, the underlying obestatin/GPR39 mechanism of action was determined using the human gastric adenocarcinoma cell line AGS." (PMID 26716511, 2016). "A recent study suggested that GPR39 expression is modulated in gastric adenocarcinoma, yet this study applied a previously incorrectly suggested ligand of GPR39 and not Zn2+." (PMID 29389900, 2018). "Altogether, our data strongly suggest the involvement of the obestatin/GPR39 system in the pathogenesis and/or clinical outcome of human gastric adenocarcinomas and highlight the potential usefulness of GPR39 as a prognostic marker in gastric cancer." (PMID 26716511, 2016). "With reference to gastric cancer, the obestatin/GPR39 system was demonstrated to regulate the proliferation of gastric adenocarcinoma cell lines." (PMID 26716511, 2016). "More importantly, the levels of GPR39 expression in these tumors provide the rationale for including GPR39 as a prognostic marker of human gastric adenocarcinomas." (PMID 26716511, 2016). "In the present study, we determined the expression levels of the obestatin/GPR39 system in human gastric adenocarcinomas and explored their potential functional roles." (PMID 26716511, 2016). "For this purpose, we studied the expression pattern and significance of the obestatin/GPR39 system in human gastric adenocarcinomas." (PMID 26716511, 2016). "We propose that the obestatin/GPR39 system displays an enhancer role in the development and progression of gastric adenocarcinoma." (PMID 26716511, 2016). "Of major clinical significance was the observation that the GPR39 expression found in gastric adenocarcinomas correlated with the dedifferentiation of the tumor." (PMID 26716511, 2016). "The role of obestatin/GPR39 in gastric cancer progression was studied in vitro using the human gastric adenocarcinoma AGS cell line." (PMID 26716511, 2016). "In conclusion, the present work addresses the role of the obestatin/GPR39 system in regulating motility, EMT, and invasion of gastric adenocarcinoma cells." (PMID 26716511, 2016). "For simplicity, and similar to the human gastric adenocarcinomas, we used the AGS cell line, which expresses the obestatin/GPR39 system and retains the characteristics of the parent tumor." (PMID 26716511, 2016). "In human gastric adenocarcinomas, no obestatin expression was found; however, an aberrant pattern of GPR39 expression was discovered, correlating to the dedifferentiation of the tumor." (PMID 26716511, 2016). "Third, the GPR39 pattern correlated with the dedifferentiation of gastric adenocarcinomas, and the obestatin expression was negative." (PMID 26716511, 2016).
Hyperglycemia (3 papers, 2011 to 2021). An increased concentration of glucose in the blood. "Consistent with this protective effect, GPR39 overexpression in β-cells, protects against the gradual hyperglycemia observed after low-dose STZ treatment of mice." (PMID 26720709, 2015). "However, postprandial hyperglycemia was observed in the STZ treated wild-type animals as compared to the STZ-treated GPR39 transgenic littermates after presentation of food and eating ad libitum (P = 0.037, n = 11, two way ANOVA)." (PMID 22164158, 2011). "The role of glucagon in the context of potential GPR39 driven hyperglycemia was not explored in this work since GPR39 is absent in alpha-cells." (PMID 26720709, 2015).
esophageal cancer (2 papers, 2011 to 2018). A primary or metastatic malignant neoplasm involving the esophagus. "Further study revealed that overexpression of GPR39 in esophageal cancer cells KYSE30 promoted G1/S phase transition." (PMID 21352519, 2011). "The aim of this study is to investigate the role of GPR39 in human esophageal cancer development, and to examine the prevalence and clinical significance of GPR39 overexpression in ESCC." (PMID 21352519, 2011). "The results showed that GPR39-expressing cells exhibited enhanced lamellipodia formation compared with control cells, indicating that GPR39 could induce cytoskeleton remodeling to facilitate esophageal cancer cell migration and invasion." (PMID 21352519, 2011). "Our study also provided evidence that ectopic expression of GPR39 increased ESCC cancer cell growth, indicating involvement of the GPR39 receptor in the tumorigenesis of esophageal cancer." (PMID 21352519, 2011).
gastric cancer (2 papers, 2016). A primary or metastatic malignant neoplasm involving the stomach. "Specifically, the obestatin/GPR39 system has been described to act as a pro-proliferative signal in gastric cancer cells, namely, KATO-III and AGS." (PMID 26716511, 2016). "This information led us to postulate the implication of the obestatin/GPR39 system in the development, maintenance and malignancy of gastric cancer." (PMID 26716511, 2016). "Obestatin in GPR39-bearing gastric cancer cells stimulates epithelial–mesenchymal transition and angiogenesis, as well as affecting morphology, migration, invasion, and proliferation of these cells." (PMID 28119851, 2016). "In gastric cancer, obestatin binds to GPR39 leading to the formation of a GPR39/β-arresin/Src complex, which leads to the activation of AKT signaling via EGFR transactivation." (PMID 28119851, 2016). "Obestatin, a 23-amino acid peptide encoded by the ghrelin gene, and the GPR39 receptor were reported to be involved in the control of mitogenesis of gastric cancer cell lines; however, the relationship between the obestatin/GPR39 system and gastric cancer progression remains unknown." (PMID 26716511, 2016). "Although the expression of obestatin was described in human gastric neuroendocrine tumors, no studies have provided evidence of the obestatin/GPR39 expression in other types of gastric cancer, especially adenocarcinomas, or the functional role of this system in these cancers." (PMID 26716511, 2016).
inflammatory bowel disease (2 papers, 2018 to 2021). A spectrum of small and large bowel inflammatory diseases of unknown etiology. "In contrast, local pH changes during inflammatory bowel disease may attenuate ZnR/GPR39-dependent cell proliferation in the digestive system and may contribute to epithelial erosion and barrier breakdown." (PMID 29389900, 2018). "The ZnR/GPR39-dependent enhancement of junctional complex proteins ZO-1 and occludin suggested that ZnR/GPR39 may be involved in ameliorating symptoms of inflammatory bowel diseases." (PMID 29389900, 2018). "Moreover, activation of GPR39 has been demonstrated to promote wound healing, ameliorate symptoms of inflammatory bowel diseases, dampen epileptic seizure activity, reduce anxiety-like behaviors and regulate insulin secretion and malignant progression of several cancers." (PMID 34645465, 2021).
ovarian carcinoma (2 papers, 2018 to 2022). A malignant neoplasm originating from the surface ovarian epithelium. "Lastly, GPR39 is frequently overexpressed in ovarian cancer tissue and mediates Zn2+ induced signaling." (PMID 35625966, 2022). "GPR39 was found to be an inhibitor of cell death, hence representing a potential therapeutic target for the treatment of ovarian cancer." (PMID 35625966, 2022).
Stroke (2 papers, 2022 to 2023). Sudden impairment of blood flow to a part of the brain due to occlusion or rupture of an artery to the brain. "However, the specific relationship between GPR39, as a zinc receptor, and stroke must be further studied." (PMID 36942516, 2023). "Furthermore, these results provide both an insight into how the obestatin/GPR39 system regulates anti-apoptotic pathways, and a framework for ascertaining how this system can be optimally targeted in treatment of brain cell death after stroke." (PMID 33400083, 2022).
acute myocardial infarction (1 paper, 2026). Necrosis of the myocardium, as a result of interruption of the blood supply to the area. "Our aim was to determine whether selective pharmacological blockade of GPR39 by the novel drug, VC108, reduces no reflow (NRV) and infarct (INV) volumes acute myocardial infarction (AMI)." (PMID 41648575, 2026).
cardiac hypertrophy (1 paper, 2023). "GPR39 overexpression in neonatal cardiomyocytes exacerbates angiotensin II-induced cardiac hypertrophy." (PMID 37108314, 2023).
colorectal adenocarcinoma (1 paper, 2022). The most common type of colorectal carcinoma. "In primary colonic cells and human colorectal adenocarcinoma-derived Caco-2 cells, ZnR/GPR39 enhances Cl− transport by upregulating KCC1." (PMID 36292986, 2022).
diarrhoea (1 paper, 2021). "After activation by Zn2+, ZnR/GPR39 controls the absorption of Cl− and reduces fluid loss during diarrhoea by upregulating potassium-chlorine cotransporter 1 in the basolateral colon." (PMID 33663613, 2021).
Dry skin (1 paper, 2021). Skin characterized by the lack of natural or normal moisture. "Finally, we found that the expression of GPR39 (a zinc-sensing GPCR) was significantly upregulated in the dry skin mice model and involved in the pathogenesis of chronic itch." (PMID 35095413, 2021).
Duchenne muscular dystrophy (1 paper, 2026). Duchenne muscular dystrophy (DMD) is a neuromuscular disease characterized by rapidly progressive muscle weakness and wasting due to degeneration of skeletal, smooth and cardiac muscle. "In this study, we investigated the molecular mechanism by which the obestatin/GPR39 system, an autocrine signaling with anabolic impact on normal skeletal muscle, restores autophagy in Duchenne muscular dystrophy (DMD)." (PMID 41541654, 2026).
gastric ulcer (1 paper, 2018). An ulcerated lesion in the mucosal surface of the stomach. "As such, a role for ZnR/GPR39 may also underlie the healing effects of Zn2+ on gastric ulcers." (PMID 29389900, 2018).
Glucose intolerance (1 paper, 2011). Glucose intolerance (GI) can be defined as dysglycemia that comprises both prediabetes and diabetes. "Mice deficient in the zinc-sensor GPR39, which has been demonstrated to protect cells against endoplasmatic stress and cell death in vitro, display moderate glucose intolerance and impaired glucose-induced insulin secretion." (PMID 22164158, 2011).
Insulin resistance (1 paper, 2022). Increased resistance towards insulin, that is, diminished effectiveness of insulin in reducing blood glucose levels. "The effect is in part related to the role of GPR39 in pancreatic cell hyperplasia associated with the development of insulin resistance." (PMID 35875352, 2022). "GPR39 augments insulin secretion under conditions of increased demand; e.g., age-dependent and diet-induced insulin resistance." (PMID 35875352, 2022).
itch (1 paper, 2021). "The causal relationship between GPR39 activation and ERK phosphorylation in the skin under chronic itch conditions warrants further investigations." (PMID 35095413, 2021). "Given GPR39 as a Zn2+-sensing GPCR, we predicted that GPR39 may also be involved in Zn2+-induced itch in mice." (PMID 35095413, 2021). "Thus, we demonstrated that the zinc/TRPA1/GPR39 axis played a critical role in Zn2+-induced acute and chronic itch in mice." (PMID 35095413, 2021). "Therefore, we speculated that under chronic itch conditions, endogenous Zn2+ was sensed by GPR39 in the skin, and the activation of GPR39 may lead to the production or release of proinflammatory and pruritogenic mediators from the keratinocytes, which contributes to the development of chronic itch." (PMID 35095413, 2021). "We further investigated whether the zinc-sensing receptor, GPR39 was involved in acute or chronic itch in mice." (PMID 35095413, 2021). "Together, these results indicated that the TRPA1/GPR39/ERK axis mediated the zinc-induced itch and, thus, targeting zinc signaling may be a promising strategy for anti-itch therapy." (PMID 35095413, 2021). "This raised another interesting question whether extracellular Zn2+ sensed by GPR39 in the skin is involved in wound healing-induced itch or not." (PMID 35095413, 2021).
lymph node metastasis (1 paper, 2011). "The results showed that overexpression of GPR39 was significantly associated with lymph node metastasis (P = 0.008) and advanced clinical stage (P = 0.004)." (PMID 21352519, 2011). "We found that GPR39 was frequently overexpressed in primary ESCCs in both mRNA level (27/50, 54%) and protein level (121/207, 58.5%), which was significantly associated with the lymph node metastasis and advanced TNM stage (P < 0.01)." (PMID 21352519, 2011).
migraine (1 paper, 2019). "The associations of six SNPs identified from our previous study, including TRPM8 rs10166942, LRP1 rs1172113, DLG2 rs655484, GFRA1 rs3781545, UPP2 rs7565931, and GPR39 rs10803531, and migraine endophenotypes, including chronic migraine and allodynia were tested." (PMID 31842742, 2019).
osteoporosis (1 paper, 2025). A condition of reduced bone mass, with decreased cortical thickness and a decrease in the number and size of the trabeculae of cancellous bone (but normal chemical composition), resulting in increased fracture incidence. "Targeting GPR39 may offer novel therapeutic strategies for osteoporosis and other bone disorders characterized by impaired matrix remodeling." (PMID 41041978, 2025).
postmenopausal osteoporosis (1 paper, 2025). Metabolic disorder associated with fractures of the femoral neck, vertebrae, and distal forearm. "Building upon earlier evidence demonstrating that GPR39 supports trabecular bone mass and matrix quality in male mice, the present work expands these findings by characterizing its role in female and ovariectomized (OVX) mice—models pertinent to postmenopausal osteoporosis." (PMID 41041978, 2025).
prostate tumor (1 paper, 2020). "Thus, restoration of zinc levels and, thereby, prevention of low citrate concentrations, together, may prevent ZnR/GPR39 mediated enhancement of prostate tumor growth." (PMID 32850402, 2020).
ulcerative colitis (1 paper, 2023). An inflammatory bowel disease involving the mucosal surface of the large intestine and rectum. "Furthermore, in an ulcerative colitis model, ZnR/GPR39 could enhance the restoration of occludin expression by activating intracellular Ca2+ signaling, which is important for the restoration of the intestinal barrier." (PMID 36942516, 2023).
xerostomia (1 paper, 2019). Dryness of the mouth resulting from reduced salivary secretion. "Our finding that ZnR/GPR39 induces salivary secretion independent of muscarinic signaling may provide therapeutic insight into xerostomia due to muscarinic dysfunction." (PMID 31776425, 2019).